IFT140 (intraflagellar transport 140)
Diseases named in the same sentence as IFT140 in open-access papers (continued):
Sharing a sentence is not in itself a finding about the gene and the disease.
polycystic kidney disease (5 papers, 2013 to 2025). A usually autosomal dominant and less frequently autosomal recessive genetic disorder characterized by the presence of numerous cysts in the kidneys leading to end-stage renal failure. "The proportion of monoallelic loss-of-function IFT140 variants in this cohort was higher than that in previously reported cohorts with polycystic kidneys who had a positive family history." (PMID 39291187, 2024). "Another multi-group study led by the Harris laboratory found monoallelic loss-of-function IFT140 mutations in patients with mild polycystic kidney disease with limited kidney insufficiency." (PMID 35832738, 2022). "A targeted deletion of Ift140 in collecting ducts results in polycystic kidneys beginning around postnatal day 5 consistent with the previous association of IFT140 mutations with a range of kidney pathologies including cysts." (PMID 24009529, 2013). "Due to the mild phenotype of polycystic kidney disease associated with the IFT140 gene, renal disease in parents may go unnoticed." (PMID 40428294, 2025). "The mild phenotype of polycystic kidneys due to IFT140 may cause parental kidney disease to be overlooked." (PMID 39291187, 2024). "Therefore, previous studies and the current one show that the presence of atypical kidney cysts and the absence of hepatic cysts, despite kidney enlargement, can be a characteristic of polycystic kidneys caused by the IFT140 variant." (PMID 39291187, 2024). "Because the phenotype of polycystic kidneys caused by the IFT140 gene is mild, parental kidney disease may be overlooked." (PMID 39291187, 2024). "In conclusion, at least 4.5% of adult patients with polycystic kidneys whose parents do not have evident polycystic kidneys have monoallelic loss-of-function IFT140 variants." (PMID 39291187, 2024). "The proportion of PKD1 or PKD2 pathogenic variants in patients without a positive family history of polycystic kidneys is low, and the presence of IFT140 pathogenic variants is significant." (PMID 39291187, 2024). "Adult patients with polycystic kidneys whose parents do not have evident polycystic kidneys may have more IFT140 pathogenic variants than those with a family history of polycystic kidneys." (PMID 39291187, 2024). "Therefore, the proportion of patients with pathogenic variants in IFT140 is particularly high and cannot be ignored especially in the case of being limited to the cases without a positive family history of polycystic kidneys." (PMID 39291187, 2024). "Therefore, the high proportion of IFT140 pathogenic variants in cases without a positive family history of polycystic kidneys may be attributed not only to novel variants but also to the possibility that their parents were not diagnosed due to their milder phenotype." (PMID 39291187, 2024).
chronic kidney disease (4 papers, 2020 to 2025). Impairment of the renal function secondary to chronic kidney damage persisting for three or more months. "In the previous study on genetic analysis of ADPKD-diagnosed families, patients with IFT140 pathogenic variants had a milder chronic kidney disease course than those with PKD2 pathogenic variants." (PMID 39291187, 2024). "Our studies confirm that IFT140 changes in patients with CED are associated with early onset end-stage renal disease." (PMID 32007091, 2020). "We also report a subject with a dual molecular diagnosis, BO-133, who had chronic kidney disease (stage IV at 78 years) with multiple bilateral cysts and diabetes mellitus: he had a frameshift variant in IFT140, but he was also found to have a whole gene deletion of HNF4A associated to MODY type 1." (PMID 40428294, 2025). "We conclude that progressive and end-stage renal disease may have an early onset in CED patients with IFT140 variants." (PMID 32007091, 2020). "We found that individuals affected by Sensenbrenner syndrome and IFT140 defects developed early onset end-stage renal disease." (PMID 32007091, 2020).
cranioectodermal dysplasia (4 papers, 2017 to 2023). Cranioectodermal dysplasia (CED) is a rare developmental disorder characterized by congenital skeletal and ectodermal defects associated with dysmorphic features, nephronophthisis, hepatic fibrosis and ocular anomalies (mainly retinitis pigmentosa). "WDR35 and IFT122 genes are most commonly mutated in Sensenbrenner syndrome, and variants in the IFT140 gene are a rare cause of CED." (PMID 32007091, 2020). "Additionally, according to recent publications, the IFT140 gene is associated with another newly described phenotype called Cranioectodermal dysplasia or Sensenbrenner syndrome." (PMID 37628605, 2023). "To date, more than 60 patients have been reported in literature and mutations in six genes have been associated with Sensenbrenner syndrome: IFT122, WDR35, IFT140, IFT43, IFT52 and WDR19." (PMID 32007091, 2020).
retinal degeneration (4 papers, 2018 to 2023). Degeneration of the retina. "A major finding is that IFT88, IFT57 and IFT140 are depleted gradually after deletion of CEP164 at P16-P21, implicating IFT malfunction as the cause of retina degeneration in rodCep164-/- mice." (PMID 36074756, 2022).
Bardet-Biedl syndrome (3 papers, 2022 to 2024). A ciliopathy with multisystem involvement. "This variant was found in a sporadic case with rod-cone dystrophy and clinical signs of Bardet-Biedl syndrome in which 2 likely pathogenic variants have been identified in the IFT140 gene; segregation analysis was not possible to establish the phase of any of these alleles." (PMID 38184646, 2024).
cyst (3 papers, 2020 to 2024). A sac-like closed membranous structure that may be empty or contain fluid or amorphous material. "In cases with pathogenic variants in IFT140, kidney cysts were asymmetrical, with many atypical instances of 1 large cyst." (PMID 39291187, 2024).
end-stage renal failure (3 papers, 2020 to 2024). "In comparison to other IFT140-cranioectodermal patients, our proband had similar skeletal features among with early onset end-stage renal failure that required kidney transplantation but did not have common ophthalmological features such as retinopathy, optic nerve atrophy, or nystagmus." (PMID 37628605, 2023).
dysplasia (2 papers, 2023 to 2025). A usually neoplastic transformation of the cell, associated with altered architectural tissue patterns. "Using these examples, we emphasize the importance of tandem duplication screening in patients with clinically suspected IFT140-associated dysplasia when only one genetic variant was detected in the IFT140 using NGS methods." (PMID 37628605, 2023).
Hepatic cysts (2 papers, 2024 to 2025). "In the same study, out of 66 patients with IFT140 pathogenic variants, only 9 (14%) had liver cysts and 2 (3%) had PLD." (PMID 39291187, 2024). "Recent reports described IFT140 in ADPKD-like phenotypes, including both kidney and liver cysts, and suggesting a link in > 1% of cases." (PMID 39928271, 2025). "Interestingly, only 1 patient with pathogenic IFT140 variants had liver cysts, but none had PLD." (PMID 39291187, 2024).
Hepatic fibrosis (2 papers, 2022 to 2025). The presence of excessive fibrous connective tissue in the liver. "The CISTR, IFT140, and RGS14 genes are potential novel candidate BDM biomarkers for liver fibrosis and these pilot data suggest further work on BDM biomarkers is warranted." (PMID 35433752, 2022). "The CISTR, IFT140, and RGS14 genes are likely novel candidate blood methylation biomarkers for the diagnosis of liver fibrosis in NAFLD." (PMID 35433752, 2022). "A novel homozygous IFT140 variant was discovered in a 1.5-year-old girl who was evaluated for CKD stage 4 with small kidneys without cystic pattern, hepatic fibrosis, neurological developmental delay, and unilateral moderate sensorineural hearing loss." (PMID 40337643, 2025). "Genes such as CISTR, IFT140, and RGS14 that contain DMPs in the blood DNA of NAFLD patients may provide clues to investigate the role of DNA methylation in the progression of liver fibrosis." (PMID 35433752, 2022). "The roles of the CISTR, IFT140, and RGS14 genes in the onset of liver fibrosis in NAFLD patients and their roles in the blood and the relationship with liver fibrosis remain unclear." (PMID 35433752, 2022). "Therefore, the CISTR, IFT140, and RGS14 genes may be potential novel candidate blood methylation biomarkers for the diagnosis of liver fibrosis in NAFLD." (PMID 35433752, 2022).
Joubert syndrome (2 papers, 2017 to 2023). Joubert syndrome (JS) is characterized by congenital malformation of the brainstem and agenesis or hypoplasia of the cerebellar vermis leading to an abnormal respiratory pattern, nystagmus, hypotonia, ataxia, and delay in achieving motor milestones. "In cilia, RPI-1/DCDC2 colocalizes with ciliary proteins such as CEPH-41 (the homolog of Joubert syndrome-associated CEP41) and IFT-140 (the homolog of human IFT140)." (PMID 37529113, 2023).
Kidney Cyst (2 papers, 2024 to 2025). Abnormal fluid filled sac within the kidney, either acquired or congenital. "In our study, some patients with a monoallelic IFT140 loss-of-function variant had asymmetric kidney cysts (Patient ID." (PMID 39291187, 2024). "Of 157 patients, 7 had parents with simple kidney cyst (1 with the IFT140 pathogenic variant, 3 with the PKD1 or PKD2 pathogenic variant, 1 with the OFD1 pathogenic variant, and 2 without pathogenic variants)." (PMID 39291187, 2024). "Furthermore, in patients with IFT140 pathogenic variants, each kidney cyst was larger than those typically seen in ADPKD, with some patients exhibiting asymmetrical kidney cysts." (PMID 39291187, 2024).
male infertility (2 papers, 2022 to 2023). The inability of the male to effect fertilization of an ovum after a specified period of unprotected intercourse. "Mutations in other IFT-B gene additional to IFT74 (IFT81, IFT20, IFT27, IFT172), and in IFT-A genes (IFT140) can cause spermatogenesis defects and male infertility in mice." (PMID 37555648, 2023). "Additionally, deficiency in IFT74, IFT81, IFT140, and IFT172 have been proven to be related to spermiogenesis defects and male infertility." (PMID 36321563, 2022).
pancreatic cancer (2 papers, 2021 to 2023). "Just recently, a region on chromosome 16, near IFT140, has been described as differentially methylated and associated with pancreatic cancer risk in an epigenome-wide association study." (PMID 37885041, 2023). "IFT140, is required for cell motility, and its promoter hypermethylation serves as a risk factor for pancreatic cancer." (PMID 34885197, 2021).
atrioventricular septal defect (1 paper, 2023). "Another study describing patients with an atrioventricular septal defect showed compound heterozygous variation in IFT140." (PMID 36586055, 2023).
autosomal dominant polycystic kidney disease (1 paper, 2024). "Recently, the monoallelic loss-of-function IFT140 variant was identified as a causative gene for autosomal dominant polycystic kidney disease (ADPKD)." (PMID 39291187, 2024).
autosomal recessive retinitis pigmentosa (1 paper, 2023). Autosomal recessive retinitis pigmentosa (RP) is an autosomally recessive inherited retinal dystrophy leading to progressive loss of the photoreceptors and retinal pigment epithelium and resulting in blindness usually after several decades. "Mutations in IFT140 lead to autosomal recessive retinitis pigmentosa (ASRP)." (PMID 36833373, 2023).
Cystic Nephroma (1 paper, 2025). A benign encapsulated neoplasm of the kidney, characterized by the presence of cysts separated by septa. "At the time of this publication (March 2025), the only reported pediatric case in the literature was that of a 6-year-old girl with cystic nephroma and a heterozygous deletion of exon 13 in the IFT140 gene." (PMID 40428294, 2025).
dwarfism (1 paper, 2023). "In another study, the deletion of Ift140 in mice resulted in dwarfism, including reduced bone mass and shortened femoral length." (PMID 36586055, 2023).
Hearing impairment (1 paper, 2018). A decreased magnitude of the sensory perception of sound. "This suggests that pathogenic variants in IFT140 could underlie the hearing impairment present in this patient." (PMID 30479745, 2018).
Hydrocephalus (1 paper, 2025). Hydrocephalus is an active distension of the ventricular system of the brain resulting from inadequate passage of CSF from its point of production within the cerebral ventricles to its point of absorption into the systemic circulation. "The Ift140 cKO mice did not exhibit any signs of gross hydrocephalus." (PMID 40348912, 2025). "No instances of hydrocephalus or situs inversus were observed in these mice and cilia in the brain ventricles appeared unaffected as indicated by immunostaining of ependymal cilia in control and Ift140 cKO mice." (PMID 40348912, 2025). "The first generation of Ift140 cKO mice (Ift140flox/flox; FOXJ1-Cre±) did not exhibit gross abnormalities such as hydrocephalus, and they had normal left–right asymmetry." (PMID 40348912, 2025).
hydrops (1 paper, 2023). "Tbx18-Cre Ift140 deletion caused hydrops and polydactyly with high penetrance, but cardiovascular anatomy was largely unaffected except for some perimembranous VSDs." (PMID 38079449, 2023).
Hypertension (1 paper, 2024). The presence of chronic increased pressure in the systemic arterial system. "Of the 7 patients with the IFT140 pathogenic variants, 6 were men, and 6 had hypertension." (PMID 39291187, 2024).
Infertility (1 paper, 2025). "We reported that conditional deletion of IFT140 in spermatocytes and spermatids resulted in infertility, implicating a requirement for IFT-A component in mammalian motile ciliogenesis in sperm." (PMID 40348912, 2025). "Likewise, IFT81 male mice were infertile associated with reduced IFT-B components in testes, and others, including IFT20, IFT25, IFT27, IFT57, IFT74, and IFT88, but there was no change in the IFT-A complex protein IFT140." (PMID 40348912, 2025).
kidney enlargement (1 paper, 2024). "In a previous study on ADPKD genetic analysis, patients with IFT140 pathogenic variants frequently exhibited kidney enlargement." (PMID 39291187, 2024).
MODY (1 paper, 2025). "The association of MODY with a renal cystic phenotype caused by an IFT140 LOF variant might have accelerated the decrease in renal function." (PMID 40428294, 2025).
polycystic liver disease (1 paper, 2024). "None of the patients with monoallelic loss-of-function IFT140 variants had polycystic liver disease (PLD)." (PMID 39291187, 2024).
polydactyly (1 paper, 2021). A disease characterized by the presence of polydactyly, including syndromic and non-syndromic forms.
respiratory failure (1 paper, 2015). The significant impairment of gas exchange within the lungs resulting in hypoxia, hypercarbia, or both, to the extent that organ tissue perfusion is severely compromised. "Furthermore, all affected individuals died from respiratory failure and a severe short rib phenotype which is not observed in individuals with IFT140, IFT172 or IFT80 mutations." (PMID 25361962, 2015).
retinal disease (1 paper, 2020). "Signs of retinal disease have been reported in patients with variants in IFT140." (PMID 32007091, 2020).
renal disease (6 papers, 2018 to 2025). "IFT140 is associated with autosomal recessive Mainzer-Saldino syndrome, a disorder characterized by kidney disease, eye problems and skeletal abnormalities." (PMID 33407854, 2021). "We identified compound heterozygous causal variants in IFT140 in two unrelated Polish CED patients with early onset renal disease." (PMID 32007091, 2020). "So far only one male and one female patient with IFT140 variants were described in the literature and both developed early onset of renal disease and received a kidney transplant." (PMID 32007091, 2020). "Defects to the IFT-A complex of proteins (e.g., WDR35, IFT122, IFT43, IFT172, IFT140 and WDR19), can present with renal disease phenotypes such as chronic renal failure, NPHP, and renal cysts and, in some cases, isolated NPHP or NPHP-like nephropathy." (PMID 38292052, 2023).
cancer (1 paper, 2022). A tumor composed of atypical neoplastic, often pleomorphic cells that invade other tissues. "The top 100 JMJD8 coexpressed genes in pan-cancer were analyzed on GEPIA2.0, and the top 5 genes (C16ORF58, IFT140, ITFG3, PIGQ, and WDR24) showed high correlations with JMJD8 in the majority of cancer types." (PMID 35898493, 2022).
IFT140 also shares sentences with these, for which no sentence is quoted: nephronophthisis (3 papers); cone-rod dystrophy (2); Leber congenital amaurosis (2); Opitz trigonocephaly C syndrome (2); APRT deficiency (1); autosomal dominant tubulointerstitial kidney disease (1); Ayme-Gripp syndrome (1); Batten disease (1); cone dystrophy (1); developmental delay (1); diabetes mellitus (1); diaphragmatic hernia (1); familial hypercholesterolemia (1); Fanconi anemia (1); female infertility (1); focal segmental glomerulosclerosis (1); genetic disease (1); glomerular diseases (1); Hypocalcemia (1); Hypomagnesemia (1); idiopathic infantile hypercalcemia (1); kidney (1); kidney failure (1); microcephaly (1); myopia (1); Nystagmus (1); Obesity (1); oligoasthenoteratozoospermia (1); omphalocele (1); Onset (1).
A further 9 diseases each share a sentence with IFT140 in 1 paper.